CCL2 (C-C motif chemokine ligand 2)
Diseases named in the same sentence as CCL2 in open-access papers (continued):
Sharing a sentence is not in itself a finding about the gene and the disease.
tumor (continued). "The recombinant ligands CCL22 and CCL2 in this study were used in concentrations of 50 ng/mL, and it is not clear from our data what concentration will be required in vivo to efficiently reroute immune cells towards tumor sites." (PMID 36834542, 2023). "For example, CCL2 derived from tumor cells recruit CCR2+ myeloid cells; hence CCR2 antagonist could directly reduce TAM infiltration and improve the efficacy of ICB in murine GBM." (PMID 37731483, 2023). "Tumor volumes increased in an early phase in response to anti-CCL2 Ab treatment but rapidly reverted over time and resulted in the inhibition of primary tumor growth, suggesting that CCL2 neutralization may act in a biphasic manner." (PMID 37208442, 2023). "We hypothesized that CCL2 may promote TAMs infiltration in testicular tissue and induce tumor generation by regulating MMPs." (PMID 37352031, 2023). "CCL2 promotes tumor invasion and metastasis by recruiting mononuclear macrophages." (PMID 36959811, 2023). "Consistently, loss of endothelial CCL2 or tumor cell CCR2 normalized the reduced tumor growth seen in mice lacking endothelial CALCRL or Gs." (PMID 36374225, 2023). "The incremental process of bone metastasis development is initiated by establishing a premetastatic niche at distant organs created by several tumor-derived factors (CCL2, IL6, lysyl oxidase (LOX), and Dickkopf WNT signaling pathway inhibitor 1 (DKK1)) of the primary tumor." (PMID 37296869, 2023). "Moreover, activated NF‐κB signaling promoted CCL2 secretion in tumor cells, leading to further monocyte recruitment and replenishment of the Mφ population, which maintained the malignant feedback loop." (PMID 37009412, 2023). "Moreover, qRT-PCR analysis showed higher levels of the cytokine CCL2 in the hearts of tumor-bearing mice." (PMID 37759510, 2023). "It is worth noting that discontinuing CCL2 inhibition can worsen tumor metastasis, although the mechanism remains unclear." (PMID 37915048, 2023). "Additionally, IL6 and CCL2 were induced in CAFs upon co-culture with patient matched tumor organoids to a greater extent than in NFs along with the activation of NFκB target genes." (PMID 37460545, 2023). "It remains to be evaluated whether promoting endothelial CCL2 formation in adrenomedullin-producing tumors is a strategy to reduce tumor growth." (PMID 36374225, 2023). "The present study indicated that UVRAG could turn the tumor microenvironment to immunosuppression by secreting CCL2 to recruit macrophages, which was mediated by upregulating SP1 expression." (PMID 37173968, 2023). "Thus, we examined the role of tumor-derived CCL2 in regulating the migration activities of the MSCs." (PMID 36672395, 2023). "For example, blocking CCL2/CCR2 restricts monocytes from entering the tumor." (PMID 36941614, 2023). "In addition, upregulated FOXQ1 in tumor cells promoted the secretion of CCL2, which recruited TAMs and promoted their M2 polarization." (PMID 36841801, 2023). "Dendritic cells (DCs) can recruit macrophages to the tumor via CCL2 and CCL5." (PMID 37371612, 2023). "As the primary source of CCL2, CAFs may induce the migration of MDSCs to the tumor site through the activation of STAT3 signaling pathways." (PMID 38273859, 2023). "Il6 and Ccl2 showed a disparate behavior to acidosis in the two different tumor cell lines studied." (PMID 38069241, 2023). "In addition to its pro-angiogenic effect, adrenomedullin also inhibits endothelial formation of CCL2, which acts as an angiocrine factor and suppresses formation of adrenomedullin by tumor cells." (PMID 36374225, 2023). "Our data suggest that it might be worth determining the levels of CCL2 in tumor biopsies post-REG treatment to evaluate resistance mechanisms and provide indications for subsequent combination therapies." (PMID 37013652, 2023).
tumor (continued). "Inflammatory responses occur at the early stage after LITs, increasing the permeability of tumor vessels and promoting the injured tumor cells to produce chemokines (e.g., CCL2, CCL3, CCL4, CCL8, etc.)and proinflammatory cytokines (e.g., TNF-α, IL-1, IL-6, IL-17, etc.)." (PMID 36831664, 2023). "Furthermore, the expression of CCL2 has been confirmed to increase tumor cell proliferation through the polarization of TAMs." (PMID 37138855, 2023). "made a significant finding demonstrating that targeting the CCL2/CCR2 axis therapeutically could effectively impede the recruitment of inflammatory monocytes, inhibit tumor-associated macrophage (TAM) infiltration, and reverse M2 polarization." (PMID 38274805, 2023). "CCL2 plays a crucial role in tumor cell growth, metastasis, and host immune response." (PMID 35464849, 2022). "CCL2 binds to its cognate receptor CCR2 to mediate its tumor promoting effect." (PMID 35865534, 2022). "A fundamental outcome was the high binding affinity of the NPs to CCL2 which caused a reduction in tumour volume over the experimental period, with no evident toxicity to the healthy organs." (PMID 36678741, 2022). "For melanoma, it could be shown that PTEN-deficient cells encourage a resistance to immune infiltration by increased levels of cytokines, such as VEGFR and CCL2, resulting in an immunosuppressive tumor microenvironment." (PMID 34687436, 2022). "Given that tumor-associated macrophages (TAMs) can mediate cancer metastasis, chemotherapeutic resistance, and immune evasion through secreting CD24, CXCL8, CCL2, and other cytokines, SLC1A5 is probably involved in the formation of the immune-tolerant microenvironment." (PMID 35419359, 2022). "In most cases, CCL2 attracts immunosuppressive monocytes, which contribute to tumour progression." (PMID 35365161, 2022). "In addition, miR-580-5p can be combined with PPARA in HCC cells to stimulate the production and secretion of C-C chemokine ligand 2 (CCL2) and modify the tumor microenvironment." (PMID 35264957, 2022). "Moreover, we have also proved the mechanism that the incomplete RFA is involved in the rapid tumor progression, thus hindering the PD-1 blockade immunotherapy due to the production of CCL2 by cancer cells." (PMID 35320940, 2022). "The chemokines CCL2, CCL7, and CCL8 are expressed in many cancer types as well as cancer-associated fibroblasts (CAFs), tumor-associated macrophages (TAMs), MDSCs, and mesenchymal stem cells found in the TME, which support the tumor growth and metastasis." (PMID 35432319, 2022). "Tumor cells express less CCL2, while other cells express more." (PMID 36403055, 2022). "In diffuse-type GC, CCL2+ fibroblasts and endothelial cells were enriched in the deep invasive layer of GC compared with the superficial layer, suggesting a greater ability of tumor invasion." (PMID 36313703, 2022). "Notably, CCL2 was identified as the main cytokine controlling the formation of tumor-supportive compartment by both recruitment of tumor supportive myeloid cells and polarizing monocytes into an M2 macrophage phenotype." (PMID 36496977, 2022). "CCL2 also attracts macrophages into the tumor sites and mediates macrophage polarization." (PMID 36246629, 2022). "Therefore, we took the tumor tissues of mice in the control and SU4312 treatment group for qPCR and ELISA, and found that the expression of CCL2 significantly decreased in tumor tissues with SU4312 treatment." (PMID 36013004, 2022). "However, as a single agent, CNT0888, a humanized monoclonal antibody against CCL2, didn’t show any anti-tumor activity in mCRPC patients." (PMID 35122833, 2022). "The findings in this work suggest that the blockade of CCL2 is sufficient in the reduction of TAMs that are recruited into the tumor microenvironment and has the ability to modestly alter tumor perfusion during early-tumor response to treatment even though the overall benefit is relatively modest." (PMID 35461243, 2022).
tumor (continued). "Neutralization of the chemokine CCL2 or inhibition of colony-stimulating factor-1 (CSF-1) receptor signaling prevent monocyte infiltration into the lymph node or tumor lesions, with a consequent reduced recruitment of tumor-specific T cells and damped antitumor responses." (PMID 36230990, 2022). "There are also large amounts of tumor-associated macrophages (TAMs) existing in or around tumors, which are recruited by chemokine CCL2 released by either cancer cells or stromal cells, to participate in extracellular matrix degradation, tumor cell migration, and angiogenesis." (PMID 35693795, 2022). "Using neutralizing antibodies against CCL2 hindered the accumulation of TAMs and potentiated the anti-tumor efficacy of CD8+ T cells in the TME as the Ly6Chi monocytes were sequestered in the BM; thereby, it was shown a reduction in tumor growth and metastasis." (PMID 35664746, 2022). "Similarly, our results also confirmed that depletion of Hmga2 suppressed the expression and secretion of CCL2 in the CT26 subcutaneous tumor model by qPCR and ELISA assays." (PMID 34976223, 2022). "Tumor cells themselves as well as stromal cells can produce chemotactic molecules involved in monocyte recruitment at the tumor site, such as CC chemokine ligand 2 (CCL2) and CCL5, as well as growth factors such as vascular endothelial growth factor (VEGF) and M-CSF." (PMID 36359283, 2022). "Previously, we have demonstrated that PIPKIγ plays a variety of roles in tumors, including regulation of the Warburg effect of colon cancer 10, recruiting tumor-related macrophages via regulation of CCL2 expression 11, and regulating tumor cell PD-L1 expression in CRC cells." (PMID 35673560, 2022). "Tumor cells release a variety of chemokines, cytokines, and growth factors that subsequently lead to the recruitment of TAMs, including monocyte chemoattractant protein-2 (CCL2), which is a critical chemokine for TAM activation." (PMID 35885058, 2022). "Recent studies have suggested that CCL2 plays a major role in tumor progression and metastasis." (PMID 35464849, 2022). "In addition, various stromal cells in the TME, including endothelial cells, DCs, fibroblasts, and adipocytes, are capable of producing CCL2 to promote tumor growth and progression." (PMID 35702353, 2022). "We examined the protumor effect of tumor cell-derived CCL2 in vitro." (PMID 35851310, 2022). "Hence, CCL2 has been described to be nitrated/nitrosylated in human colon tumors and in different murine tumor models." (PMID 36429101, 2022). "CCL2 is a chemokine that attracts a number of CCR2-high-expressing monocytes to the tumor site." (PMID 35592338, 2022). "It has been reported that CCL2 mediates tumor angiogenesis in two main ways: CCL2 can bind to CCR2 directly, leading to angiogenesis, and CCL2 may indirectly promote angiogenesis through the recruitment of macrophages." (PMID 36077785, 2022). "CCL2 stimulates the growth, metastasis, and invasion of gynecological tumors, regulates the formation of the tumor microenvironment and plays a key role in tumor progression." (PMID 36403055, 2022). "In preclinical cancer model studies of breast cancer, the upregulation of CCL2 expressed by tumor cells has been found to promote the recruitment of TAMs; moreover, VEGF-C and VEGF-D secreted by TAMs have been found to promote the lymphatic metastasis of tumor cells." (PMID 36510315, 2022). "CCL2 upregulation resulted in a substantial elevation of tumor volume and weight in mouse model." (PMID 35851310, 2022). "However, removal of CCL2 blockade treatment resulted in the resumption of tumor progression since TAMs have recruited to the tumor site again." (PMID 35965509, 2022). "This study examines one major hypothesis: CCL2 blockade in the tumor microenvironment increases the sensitivity of CT26 tumors to 5-FU chemotherapy, which is quantified via longitudinal tumor growth, DRS-derived metrics and IHC analysis." (PMID 35461243, 2022).
tumor (continued). "In particular, the downregulation of CCL2 was significantly associated with the absence of macrophages in the MTA1-high tumor group." (PMID 35350571, 2022). "It indicated that high expression of CCL2 in HNSCC predicts a relatively shorter survival period, which may associate with promoted tumor progression activated by excessive CCL2." (PMID 35177591, 2022). "CCL2 facilitates tumor growth by activating the PI3K/Akt/mTOR in breast cancer." (PMID 36679900, 2022). "For example, TGF-beta is involved in the inhibition of antigen presentation, the function of antigen-presenting cells, and the activation of T cells, COX-2 and PGE2 participate in tumor growth and angiogenesis, as well as CCL2, recruits immunosuppressive cells such as regulatory T cells and MDSC." (PMID 35492352, 2022). "Additionally, in advanced PCa, CCL2 expression is notably higher in the metastatic tumor–bone microenvironment compared to that in bone-marrow adjacent to the tumor." (PMID 35406450, 2022). "On the one hand, malignant cells continue evading the immune system by secreting chemotactic tumor-promoting proteins, for example C-C motif chemokine ligand 2 (CCL2), which directs inward migration and transformation of leukocyte sub-populations (LSPs) to promote tumor initiation and promotion." (PMID 36358783, 2022). "We also showed that GATA4’s secretome was necessary for its tumor-suppressive effect by identifying the GATA4-induced secreted factor CCL2 and demonstrate that CCL2 was partially responsible for GATA4’s tumor-suppressive effects in vivo using a CCL2-targeting antibody." (PMID 35017504, 2022). "The 24-month overall survival probability in a cohort of patients with high gene expression versus low gene expression of listed chemokines in tumor specimens was 0.2 vs. 0.35 for IL-4, 0.2 vs. 0.35 for IL-10, 0.2 vs. 0.4 for CCL2, 0.2 vs. 0.57 for GM-CSF, and 0.15 vs. 0.23 for VEGF." (PMID 35884700, 2022). "Pro-inflammatory cytokines secreted by tumor cells or stromal cells, such as interleukin 6 (IL6), IL1β and C-C motif chemokine ligand 2 (CCL2), can induce phenotypic changes in tumor cells, recruit bone marrow-derived cells and form an inflammatory environment." (PMID 36158661, 2022). "CCL2 is known to promote cancer development by facilitating the attraction of microglia, circulating monocytes, and myeloid-derived suppressor cells to the tumor area, whereas GM-CSF promotes the proliferation of TIM." (PMID 35884700, 2022). "Carlumab (CNTO 888), a human IgG1κ anti-CCL2 antibody, was shown that may offer beneficial anti-tumor properties when combined with four chemotherapy regimens in preclinical studies." (PMID 36466873, 2022). "In particular, CCL2 release by cancer cells leads to the recruitment not only of tissue-resident macrophages but also of CCR2+ Ly6C hi monocytes from the bloodstream that extravasate into tumor sites and differentiate into TAMs." (PMID 35664746, 2022). "CCL2 can be secreted by CAFs and malignant cells to assist tumor progression, EMT, and migration." (PMID 36268282, 2022). "One method could be the inhibition of the recruitment of the macrophages to the tumor through the CCL2/CCR2 axis." (PMID 35565420, 2022). "We previously found that increased mitochondrial fission through upregulated Drp1 significantly induced cytosolic mtDNA stress and subsequent CCL2 secretion in HCC cells, leading to infiltration of tumor-associated macrophages into HCC tissues and tumor progression." (PMID 35209954, 2022). "Stromal cells as an essential component of the tumor microenvironment could secrete CCL-2, a chemokine that promotes tumor cell migration, proliferation and angiogenesis." (PMID 36277284, 2022). "Similarly, C-C motif chemokine ligand 2 (CCL5) can also promote the infiltration of immunosuppressive CCR5+ monocytes into the tumor site." (PMID 36139006, 2022). "Concluding, ATF4-mediated CCL2 signaling contributes to EC macrophage influx to tumor sites." (PMID 35408440, 2022).
tumor (continued). "Interestingly, we noticed that LIF and CCL2 was tightly correlated with mesenchymal subtype tumor focus in mGBM and predicted poor survival of GBM patients." (PMID 34987659, 2022). "In tumours, CCL2 can be secreted by multiple cell types, including tumour cells, myeloid-derived suppressor cells (MDSCs), mesenchymal stem cells (MSCs), tumour-associated macrophages (TAMs), tumour-associated neutrophils (TANs), and cancer-associated fibroblasts (CAFs)." (PMID 35365161, 2022). "As already mentioned, TAMs are a heterogeneous population that includes resident cells of embryonic origin present at birth and invading monocytes/macrophages recruited during early carcinogenesis by chemokines secreted by tumor and stromal cells (such as CCL2, CCL5, and CSF-1)." (PMID 35183252, 2022). "Since multiple secreted factors identified above, including AREG, PAI-1, CCL2, CCL5, IL6, IL8, and CSF2, are also known to be regulated by yes associated protein (YAP), we investigated whether V2R regulates YAP in ccRCC tumor cells." (PMID 35886951, 2022). "Additionally, we acquired a total of 6 molecules including IL6, AREG, CXCL12, TGFβ, VEGF and CCL2, which can be upregulated upon senescence, influence immune cell functions, and play tumor-promoting roles in TME30." (PMID 35361903, 2022). "When CCR2 was transduced together with a TCR specific for WT1 into CD3+ human T cells, double gene-modified CD3+ T cells demonstrated CCL2-tropic tumor trafficking and potentiated antitumor activity against WT1-expressing LK79 lung cancer cells both in vitro and in vivo." (PMID 35432319, 2022). "All these findings suggested that CCL2 is involved in carcinogenesis and tumor progression." (PMID 35177591, 2022). "As the tumor progresses, cancer cells shape the tumor infiltrate profile by secreting chemotactic factors such as CCL2 (which recruits myeloid cells), and cytokines like TGF-β and IL-10 (which promote an immunosuppressive milieu), favoring the continued growth of the tumor." (PMID 35472214, 2022). "Ccl2 is also required for the immunosurveillance of small and/or developing tumours and may play a role in tumour progression in established cancers." (PMID 36347875, 2022). "In addition, blockade of monocyte recruitment using CCL2/CCR2 inhibitors prevents MDSC accumulation in the tumor but has shown limited single-agent activity and requires combination with chemotherapeutic agents." (PMID 35179953, 2022). "Furthermore, tumor-derived chemokines and cytokines (e.g., CCL2 and MCSF) are also the pivotal stimulating factors that promote the recruitment of circulating myeloid-derived monocytes 25, which contributes to the infiltration of TAMs into tumor regions." (PMID 36451865, 2022). "In serum of CT26 tumor-bearing mice, there was extensive overlap with the factors detected in CT26-conditioned media: following mediators identified in conditioned media showed at least a 1.2-fold increase in CT26 tumor-bearing mice: IL-1α, IL-2, IL-13, CCL2/5/19, LIX, CX3CL1, CXCL1/2/10 and CCL19." (PMID 35962398, 2022). "Notably, the number of CCL2+ or CCL17+ TANs was associated with the microvascular invasion, size, differentiation, and stage of the tumor." (PMID 36077785, 2022). "There is evidence that CCL2 may lead to resistance to hormone therapy by facilitating tumor metastasis and suppressing apoptosis." (PMID 36077785, 2022). "Next, we examined CCL2 protein expression in tumor/stroma coxenografted tissues." (PMID 34874922, 2022). "Inhibiting this CCL2/CCR2 recruitment axis led to a decrease in tumor growth and vascularity." (PMID 36249052, 2022). "Indeed, CCL2 will recruit macrophages to the tumor, and induce their production of VEGF as will CCL4." (PMID 35626056, 2022). "However, when anti-CCL2 was added to the gold standard 5-FU, the overall fold change in tumor growth decreased significantly (~ sevenfold) compared to a saline control twelve days post-treatment." (PMID 35461243, 2022).